VPREB3 (V-set pre-B cell surrogate light chain 3)
Description:
Associates with the Ig-mu chain to form a molecular complex that is expressed on the surface of pre-B-cells.
Synonyms: 8HS20; N27C7-2
Tractability: Antibody: its Gene Ontology location is reachable by antibodies, with high confidence; UniProt predicts a signal peptide or a membrane-spanning region.
Gene: Protein-coding gene on chromosome 22 (23,752,743 to 23,754,425, reverse strand). Ensembl gene ENSG00000128218.
Pathways (Reactome):
Hemostasis: Cell surface interactions at the vascular wall
Gene Ontology:
Biological process: immune response
Cellular component: endoplasmic reticulum; extracellular region; immunoglobulin complex
Genetic constraint (gnomAD): Loss-of-function variants: 14 observed, 13.63 expected, observed/expected ratio (o/e) 1.03, 90% interval 0.68 to 1.59. The upper end of that interval is the gene's LOEUF score, 1.59, which puts it in group 6 of 6, group 1 being the genes least tolerant of losing a copy. Missense variants: 165 observed, 163.51 expected, observed/expected ratio (o/e) 1.01, 90% interval 0.89 to 1.15. Synonymous variants: 78 observed, 71.24 expected, observed/expected ratio (o/e) 1.1, 90% interval 0.91 to 1.32.
Homologues: Orthologues: chimpanzee VPREB3 (98% identical), macaque VPREB3 (97% identical), guinea pig VPREB3 (81% identical), rabbit VPREB3 (81% identical), dog VPREB3 (77% identical), pig VPREB3 (75% identical), mouse Vpreb3 (67% identical). Paralogues in human: IGLV5-37 (43% identical), IGLV5-45 (42% identical), IGLV11-55 (41% identical), IGLV5-52 (41% identical), IGLV2-18 (39% identical), IGLV2-11 (38% identical), IGLV2-8 (38% identical), VPREB1 (38% identical), IGLV1-40 (37% identical), IGLV1-44 (37% identical), IGLV5-48 (37% identical), IGLV7-43 (37% identical), and 81 more.
Diseases named in the same sentence as VPREB3 in open-access papers:
VPREB3 is named in the same sentence as 10 diseases in open-access papers, as found by Europe PMC text mining. Sharing a sentence is not in itself a finding about the gene and the disease. The quoted sentences say what the papers report.
B-cell lymphomas (1 paper, 2022). "The combined expression of VPREB3 and ID3 was used to develop a new helpful tool for the routine diagnosis of mature aggressive B-cell lymphomas." (PMID 36443709, 2022).
cancer (5 papers, 2017 to 2025). A tumor composed of atypical neoplastic, often pleomorphic cells that invade other tissues. "Genes characteristic of cancer cells – Oit3, Tnxb, Zfr2, VpreB3, Trim40." (PMID 28031533, 2017). "In these specific intergroup DE genes, BCL11A, VPREB3, CD79B, CHRNA7, and SWAP70 that all involved in B cell proliferation and activation, would likely impact B cell function in MDV pathogenesis and malignant tumor formation." (PMID 30922224, 2019). "Genes related to B and T cell maturation (e.g. CD37, CD79B, JCHAIN, IGLL1, VPREB3, CD52), ribosomal protein genes (RPS-*, RPL-*) and cancer/stress genes (e.g. PRAME, ARHGDIB, FOS, JUN) were within the most significantly deregulated genes between clusters in those samples." (PMID 32415257, 2020).
tumor (2 papers, 2021 to 2022). "The mBc1 cluster expressed the pre-B cell receptor-associated molecule VPREB3, the B cell activation marker CD83, and genes associated with cell metabolism, cellular growth, and tumor progression (DDX54, PRDX6, GRHPR)." (PMID 36153593, 2022). "Pre‐B lymphocyte protein 3 gene (VPREB3), which is thought to be involved in B‐cell maturation and development, was also upregulated in early CRC tumor." (PMID 33463049, 2021).
VPREB3 also shares sentences with these, for which no sentence is quoted: immune disease (2 papers); bladder cancer (1); Immunodeficiency (1); leukemia (1); lymphoma (1); myeloma (1); primary immunodeficiency (1).